TIGIT (T cell immunoreceptor with Ig and ITIM domains)
Diseases named in the same sentence as TIGIT in open-access papers (continued):
Sharing a sentence is not in itself a finding about the gene and the disease.
tumor (continued). "Predictably, TIGIT expression has mostly been found in CD3+ tumor-infiltrating lymphocytes (TILs) and peritumoral lymphocytic infiltrates, given its physiological role, highlighting an “exhausted” T-cell phenotype in a consistent proportion of cancer microenvironments." (PMID 37109579, 2023). "Furthermore, reduced expression of TIGIT resulted in reduced binding to CD155 expressed by tumor cells, thus preventing immune escape." (PMID 36913356, 2023). "Blocking TIGIT showed promising anti-tumor effects in pre-clinical studies." (PMID 37568798, 2023). "Similarly, a high TIGIT/DNAM-1 ratio on tumor-infiltrating Tregs was shown to correlate with poor clinical outcomes following ICB targeting PD-1 and/or CTLA-4." (PMID 37569880, 2023). "Tumour-infiltrating lymphocytes (TIL) express high levels of TIGIT and blocking antibodies that inhibit the TIGIT-Nectin interaction have demonstrated pre-clinical and clinical tumour control, facilitating a growing number of clinical trials targeting TIGIT across multiple cancers." (PMID 37596248, 2023). "However, in vitro evaluations confirmed that the inhibition of TIGIT augments the release of anti-tumor cytokines by CD8 + T cells." (PMID 37221555, 2023). "Importantly, the TIGIT blockade resulted in the re-polarization of M2 toward the M1 phenotype, improving the phagocytosis of tumor cells." (PMID 37444427, 2023). "Interestingly, anti-GITR antibody regulates tumor-infiltrating T cells and decreases the expression of TIGIT in combination with anti-PD-1 mAb64." (PMID 36971124, 2023). "Similar to PD-1, TIGIT is involved in inhibiting tumor directed immune responses." (PMID 35770416, 2023). "Together, DB induced very effective tumor cells lysis by effector cells that could be tendentially improved by the double blockade of TIGIT and PD-L1." (PMID 37444427, 2023). "However, in advanced tumor stages, TIGIT is up-regulated and acts as an immune checkpoint receptor, counterbalancing DNAM-1-mediated cancer cell clearance." (PMID 37629138, 2023). "Moreover, co-inhibition of TIGIT and PD-1/PD-L1 enhances anti-tumor immunity and improves treatment outcomes in various cancers in preclinical and clinical studies." (PMID 37291608, 2023). "Mounting evidence suggests that nectins interact with immune modulatory receptors, including TIGIT, and therefore higher levels of expression among certain tumor types may be explained by their role in immune regulation." (PMID 36806983, 2023). "Lastly, to determine whether blocking TIGIT could enhance the anti-tumor effect of anti-MASL CAR-T cells in vivo, six-week-old B-NDG mice were reared for subcutaneous infused of HelaCD155 cells for tumorigenesis in vivo." (PMID 37359558, 2023). "Indeed, a 2021 meta-analysis of TIGIT expression in the tumor microenvironment of various solid tumors revealed that it has prognostic value because it is associated with risk factors for OS and progression-free survival (PFS)." (PMID 35656508, 2022). "This may be a suggest that the OE19 cell line may be more resistant to the cellular stress induced by these harsh treatments compared with the OE33 cell line as PD-1 and TIGIT upregulation may be an attempt by the tumour cells to confer a survival advantage." (PMID 35245832, 2022). "Interestingly, the TIGIT+ Tregs also highly expressed IL‐32 which further promoted the migration and invasion of tumor cells." (PMID 35474948, 2022). "This study extensively looked at the effect of TIGIT blockade on macrophages in the tumor." (PMID 35656508, 2022). "This antitumor immune function of CD96 may be derived from the interaction of CD155/CD112 on tumor cells or antigen-presenting cells in the TME with TIGIT/CD96 on CD8 T cells or NK cells, resulting in the inhibition of antitumor NK cells and T cell functions." (PMID 35223835, 2022). "TIGIT is also a negative regulator of T cells that can prevent immune response against tumor." (PMID 36578079, 2022).
tumor (continued). "TIGIT is found to be expressed by tumour-infiltrating lymphocytes (TILs) in NSCLC and ‘distant lung-associated lymphocytes’ (DLALs), but also by peripheral blood mononuclear cells (PBMCs) and, less significantly, tumour-free lung lymphocytes (TFLLs)." (PMID 35328510, 2022). "The anti-tumor effect of blocking TIGIT may also need to consider the activation status of the CD226." (PMID 35433470, 2022). "To explore the role of Fc functions in its anti-tumor effects, we generated a pair of anti-TIGIT antibodies with the same variable regions, but with different Fc forms: BGB-A1217 (with wild-type IgG1 Fc), and BGB-A1217MF (with an Fc lacking FcγR binding capacities)." (PMID 35273608, 2022). "The purpose of this review is to update the role of TIGIT in cancer progression, looking at TIGIT pathways that are often upregulated in immune cells and at possible therapeutic strategies to avoid tumor aggressiveness, drug resistance, and treatment side effects." (PMID 35656508, 2022). "Therefore, TIGIT has been considered an important immune checkpoint able to inhibit several steps of the cancer immunity process, and some trials noted the good therapeutic potential of targeting TIGIT in different tumor types." (PMID 36551630, 2022). "Given the expression pattern of CD226 and CD28 on CD8+ T cell subsets that likely contribute to a robust response against tumors, optimal activation of the full repertoire of tumor-reactive CD8+ T cells is thus likely to require the coordinate inhibition of both TIGIT and PD-1." (PMID 35263569, 2022). "The binding of Fap2 to TIGIT could inhibit the activity of NK cells against the tumor cells, leading to the growth and progression of CRC." (PMID 35574378, 2022). "In an ex vivo experiment using an endometrial carcinoma cell line, ART upregulated the expression of immunosuppressive molecules such as CD155 (expressed on tumor cells) whilst downregulating TIGIT on NK cells which overall enhanced cytotoxicity when tumor and NK cells were cocultured." (PMID 36551637, 2022). "Our data also show that combination therapy of neoantigen vaccine plus anti-PD-1 modestly enhanced tumor protection which may be related to the observation that PD-1 treatment increased TIGIT expression in T cells." (PMID 36569934, 2022). "TIGIT is highly expressed on both peripheral and tumor infiltrating Treg cells." (PMID 35812451, 2022). "In addition, higher TIGIT expression was observed on tumor infiltrating Tregs than on other T-cell subtypes in TILs and some evidence has shown that TIGIT relies on Tregs to regulate the anti-tumor immune response in pre-clinical models." (PMID 35273608, 2022). "Therefore, we combined MWA and TIGIT blockade and found that the combination therapy resulted in significantly reduced tumor growth and extended long-term survival." (PMID 35320940, 2022). "However, the combined blockade of TIGIT and PD-L1 resulted in an impressive 75% decrease in tumor volume, with the majority of mice achieving a complete response and a 75% survival rate (compared to 10% for anti-TIGIT monotherapy)." (PMID 35327475, 2022). "On the other side of the spectrum, TIGIT deficient mice showed retarded progression in different murine tumor models although metastatic spread was not affected." (PMID 35410311, 2022). "Given that CD155 is expressed on NK cells and T cells, TIGIT on tumor cells may transmit inhibitory signals to immune cells via the interaction with CD155." (PMID 35433470, 2022). "Antibody blockade of TIGIT could inhibit NK cell exhaustion and promote NK cell dependent tumor immunity." (PMID 36159789, 2022). "TIGIT and PD-1 high co-expression was observed in PBLs (peripheral blood lymphocytes), MALs (malignant ascites lymphocytes), and TILs with increased frequency in tumor proximity in matched samples of patients at first diagnosis of ovarian cancer not treated." (PMID 35656508, 2022).
tumor (continued). "Additionally, the expression of multiple inhibitory receptors such as CTLA-4, TIGIT, LAG3, PD-1, and PD-L1 suggests that the tumor-acquired resistance was associated with T cell exhaustion in BCG-induced HLA-I+ tumors." (PMID 35503263, 2022). "The upregulation of PDL1, PDL2, HAVCR2, and TIGIT could be in an immunosuppressive status, thus facilitating tumor progression." (PMID 36698888, 2022). "Of note, tumor cell morphology seemed to determine TIGIT expression in ATC." (PMID 35971106, 2022). "However, the combination of anti-TIGIT and anti-PD-1 agents resulted in a complete tumor regression in all tested mice (n = 12)." (PMID 36497240, 2022). "Interestingly, the frequency of NK cells coexpressing PD-1 and TIGIT exhaustion markers was significantly increased in tumor compared with peripheral blood compartment." (PMID 36341402, 2022). "In addition, TIGIT also directly induces exhaustion of tumor-infiltrating NK cells with lower expression of IFNγ and TNF or indirectly contributes to exhaustion of CD8+ T cells, impairing anti-tumor immune response." (PMID 36605439, 2022). "However, when spleen cells from vaccinated tumor bearing mice were stimulated with mCAR12/mCDK12 in the presence of the anti-TIGIT antagonist antibody, more CD4 and CD8 T cells produced IFN-γ as assessed by flow cytometry." (PMID 36569934, 2022). "Considering these data, TIGIT remains to be extensively studied as a predictive marker and therapeutic agent in the clinic, especially when it comes to differentiating its role in various tumor entities such as OSCC." (PMID 36551992, 2022). "In addition, we found that TCF1−Texterm expressed higher levels of TIM-3, CTLA-4, and TIGIT, which are markers of a dysfunctional subset of tumor-infiltrating CD8+PD1+ T cells in cancer." (PMID 35153298, 2022). "Additive and/or synergistic effects after co-engagement of TIGIT and FcγRIIIA in NK cells with tumor cells suggest that several NK activatory pathways (such as DANM-1 and FcγRIIIA) may converge downstream, leading to stronger signals." (PMID 35273608, 2022). "Moreover, another study reported that the expression of TIGIT elevated in the PBMCs and tumor tissues of patients with HNSCC." (PMID 35474948, 2022). "Conversely, upon inhibition of TIGIT, PD-L1 was upregulated in the tumor immune microenvironment." (PMID 36551992, 2022). "Further research is required to fully elucidate if PD-1 or TIGIT blockade hold real potential as new treatment options and using more complex tumour models such as tumour organoids and patient-derived xenograft models to encapsulate the heterogeneous landscape of OAC will be essential." (PMID 35245832, 2022). "Our data indicate that TIGIT expression is limited to a few cell types in the TME; however, its expression is strongly associated with an upregulation of chemokine expression and an overall increased immune cell infiltration into the tumor tissue." (PMID 36551992, 2022). "This study integrally revealed the role of TIGIT in the tumor immune microenvironment." (PMID 36211383, 2022). "We also saw a correlation between tumor burden and TIGIT expression in CD4 and CD8 T cells." (PMID 34165864, 2022). "This may be important in the context of TILs expressing varying levels of CD28, CD226, PD-1, and TIGIT, and myeloid or tumor cells expressing PD-L1 and PVR." (PMID 35263569, 2022). "Although CD155 has the best affinity for TIGIT and tends to immunosuppress and reduce the activity of TIGIT expressing NK and T cells in the tumor microenvironment, the sensitivity of tumor cells to NK cell-mediated cytotoxicity is not only regulated by CD155/TIGIT." (PMID 36309698, 2022). "TIGIT is a newly discovered co-stimulatory molecule with immunosuppressive effects and acts as an emerging inhibitory receptor shared by NK and T cells and a key inhibitor in the tumor immune cycle." (PMID 36303184, 2022).
tumor (continued). "We next evaluated whether the combination treatment with anti-TIGIT and anti-PD-1 mAbs could further inhibit tumor growth in vivo." (PMID 35273608, 2022). "Tumor cells exploit the inhibitory TIGIT pathway to escape immune-mediated destruction; therefore, targeting TIGIT could be another strategy for cancer immunotherapy." (PMID 36135216, 2022). "Moreover, researchers have shown that there is synergistic action of PD-1 and TIGIT in tumour escape from immunological surveillance in a mouse model." (PMID 35328510, 2022). "Besides lymph node status, only high expression of TIGIT, PVR and PD-L1 on tumor cells remained independently associated with better RFS in multivariate analysis." (PMID 36544779, 2022). "Indeed, based on cell-to-cell communication analysis, the interaction between TIGIT on tumor cells with CD155 expressed on CD16+ monocytes was markedly increased after relapse." (PMID 36163179, 2022). "TIGIT co-inhibitory molecule is highly expressed on NK cells, CD8+ T cells and Tregs within the TME, whereas CD155 is widely expressed on tumor cells and activates TIGIT signaling to dampen NK/T cell activation and development of an effective anti-tumor response." (PMID 36428727, 2022). "Because PVR and NECTIN2 can both act on TIGIT, compared to the currently popular PDL1/PDLD1 blockers, TIGIT may not only reverse the exhaustion state of CD8 T cells but may also improve the tumor immunosuppressive microenvironment to a certain extent." (PMID 36685571, 2022). "Moreover, the Fc effector function is critical for the anti-tumor activity of BGB-A1217 in a syngeneic human TIGIT-knock-in mouse model." (PMID 35273608, 2022). "Furthermore, TIGIT is an inhibitory immune checkpoint molecule that plays role in modulating tumour-targeted T cell response and, thus, serves as potential target for immune checkpoint inhibition." (PMID 36297474, 2022). "We have also looked at studies investigating the correlation of TIGIT expression with the clinicopathological characteristics of such a tumor (such as grade, stage, and metastasis) to improve clinical diagnosis, the amount of surgical resection, prognosis determination, and target therapy." (PMID 35656508, 2022). "In addition to that, the triple therapy group reduced lung metastases’ counts in this high-tumor-burden and aggressively spreading 344SQ-P model when compared to RadScopal alone (p = 0.0297) or immunotherapy alone (α-TIGIT + α-PD1, p = 0.0477)." (PMID 35008385, 2022). "Similarly, we found that in KPC4580P tumor bearing mice, the majority (80%) of the TIGIT+ cells also express PD-1 but low levels of CD226." (PMID 36569934, 2022). "Expression levels of immune checkpoint proteins such as PD-1, CTLA-4, TIM-3 and TIGIT, and checkpoint ligands including PD-L1 and galectin-9 are higher in peripheral blood or tumor tissue for CRC patients, compared with blood or colon tissue from healthy donors." (PMID 35874729, 2022). "Furthermore, a dual blockade of TIGIT and PD-1/PD-L1 pathways was shown to result in tumour rejection even in tumour models resistant to anti-PD-1 therapy." (PMID 36297474, 2022). "Fc function is required for the ADCC function and may augment TIGIT antibody’s activity in the anti-tumor immune response through Treg reduction." (PMID 35273608, 2022). "Further studies are necessary to determine if PD-1 and TIGIT tumour cell intrinsic signalling may regulate OAC cell metabolism." (PMID 35245832, 2022). "Interestingly, the shifts in Treg and anti-tumor T cell expression were accompanied by increased expression of the exhaustion markers PD-L1 (3.83-fold, p=0.011), TIGIT (3.61-fold, p=0.011), and tumor suppressor FBP1 (9.23-fold, p=0.013) in women." (PMID 36387163, 2022). "Expression of TIGIT on tumor-infiltrating T cells results in exhaustion of tumor immunity." (PMID 35572593, 2022).
tumor (continued). "Thus, the use of TIGIT as a target molecule is a promising strategy for neoplasm therapy, especially in combination with the inhibition of other immune cell receptors." (PMID 36140182, 2022). "In addition, we found TIGIT expression in the tumor (r=-0.52, p=0.04) and FOXP3 in N1 ntbLNs (r=-0.56, p=0.03) to be correlated with TIDE scores." (PMID 35833140, 2022). "In addition, T cells also express LAG-3, TIM-3, TIGIT, and other receptors, and these immunosuppressive receptors are potential therapeutic targets and have seen anti-tumor efficacy in preclinical studies." (PMID 36225938, 2022). "In this report, we have shown that BGB-A1217, a clinical stage anti-human TIGIT mAb, could elicit strong immune responses and potent anti-tumor efficacies in vitro and in vivo." (PMID 35273608, 2022). "On the contrary, TIGIT blockade antibodies restored anti-tumor activity." (PMID 36578079, 2022). "Interestingly, this study also found that the co-blockade of TIGIT and PD-1 reduced the number of tumor-infiltrating DCs in this model." (PMID 35327475, 2022). "Furthermore, several studies on mice as well as in vitro experimental studies support the notion that dual inhibition of CD112R and TIGIT increases anti-tumor immunity." (PMID 36231109, 2022). "Importantly, the results demonstrated that TIGIT blockade was able to directly subvert the exhaustion of tumor-infiltrating NK and T cell." (PMID 36230485, 2022). "TIGIT+ Tregs highly expressed IL‐32 and promoted the migration and invasion of tumor cells." (PMID 35474948, 2022). "Moreover, the strong correlation between CD79A and risk score, B cells, T cells, TIGIT, BTLA, CD27, and TNFRSF17 revealed the crucial role of CD79A in regulating the tumor microenvironment (TME) in LUAD patients." (PMID 35295857, 2022). "Moreover, we evaluated the antitumor functions of MWA alone or in combination with TIGIT blockade by monitoring tumor growth and survival of the mice." (PMID 35320940, 2022). "In addition, LAG-3, TIGIT, and PD-1 are co-expressed on the surface of T cells and are all immune checkpoint ligands subject to tumor immunosuppression." (PMID 35892835, 2022). "A recent study using fusion protein demonstrated the relationship between TIGIT and Nectin4, which is composed of the Fc part of human IgG1 and the extracellular part of a variety of tumor markers, including Nectin4, then stained NK cells to confirm that Nectin4 is a TIGIT ligand." (PMID 35720417, 2022). "Taken together, all evidences indicate that targeting TIGIT, and further in combination with other immune checkpoint blockade therapies, may augment immune responses and achieve optimal anti-tumor efficacy." (PMID 35273608, 2022). "LAG3, TIM-3, and TIGIT expression seemed to be mutually exclusive within the tumor microenvironment and could be used to be define distinct tumor subtypes." (PMID 36313654, 2022). "Thus, there were increased frequencies of NK cells coexpressing PD-1 and TIGIT in the tumor microenvironment." (PMID 36341402, 2022). "To further investigate the relationship between KIRP tumor immunity, we performed the correlation analysis between KIRP immune checkpoint genes (CTLA4, HAVCR2, PDCD1, PDCD1LG2, and TIGIT) and high mutation frequency genes (TTN, MET, KMT2C, PKHD1, SETD2, and KMT2D)." (PMID 36618928, 2022). "The blockade of TIGIT has been shown to prevent the depletion of NK cells and stimulate NK-mediated tumor immunity, activate antitumor T-cell immunity, and promote the formation of immune memory in models of tumor retransplantation." (PMID 36140182, 2022). "Furthermore, TIGIT was validated to be expressed on MCL tumor cells after BA relapse and TIGIT expression on tumor cells suppressed IFNγ production by T cells." (PMID 36163179, 2022). "Clinical relevance of TIM-3 and TIGIT expressions on tumor cells." (PMID 36561512, 2022). "The DNAM-1/TIGIT/CD96 pathways offer new ways to improve immune-cell anti-tumor response." (PMID 36059606, 2022).